RPS3 (ribosomal protein S3)
Diseases named in the same sentence as RPS3 in open-access papers (continued):
Sharing a sentence is not in itself a finding about the gene and the disease.
infection (60 papers, 2008 to 2025). The state of being infected such as from the introduction of a foreign agent such as serum, vaccine, antigenic substance or organism. "An increasing number of studies suggest that the RPS3/NF-κB signaling pathway is vital in the host proinflammatory transcription and immune responses against infection by A/E pathogens." (PMID 25756944, 2015). "Overall, these infection and transfection experiments suggest that NleH1 specifically inhibits RPS3-dependent gene expression." (PMID 20041225, 2009). "To verify that RPS3 interacts with NleH1, we used an a-RPS3 antibody to immunoprecipitate RPS3 from cell lysates obtained after infection with EPEC UMD207 [eae-/bfp-;] strains expressing FLAG-tagged NleH1, NleH2, or a control FLAG epitope." (PMID 20041225, 2009). "These expression peaks may suggest the significant roles of endonucleases during host infection and independent roles for invasive endonucleases/introns and rps3 genes." (PMID 34616376, 2021). "In conjunction with our previous studies showing that NleH1 attenuates RPS3 Ser209 phosphorylation, our results highlight the critical role of the RPS3/NF-κB signaling pathway in the host immune response to A/E pathogen infections." (PMID 25756944, 2015). "Additionally, transcription of both the NFKBIA and TNFIAP3 genes were upregulated more in ΔescN and ΔnleH1, compared with wild-type and ΔnleH2 infections, also suggesting a role for NleH1 in transcriptional inhibition of these RPS3-dependent genes." (PMID 20041225, 2009). "We propose that NleH1-reduction of RPS3 nuclear abundance in response to PAMP detection may explain previously documented findings that IL-8 expression is suppressed at early stages of infection, even in the context of NF-κB Rel protein nuclear translocation and increased DNA-binding activity." (PMID 20041225, 2009). "Flow cytometric analysis performed at 24 h post-infection revealed that silencing of RPL19, RPS3 and DDOST significantly impaired both YFV and WNV replication." (PMID 30650657, 2019). "We observed that under all the conditions tested (mock infection, 6 hpi, and 18 hpi), cytoplasmic ribosome proteins from the small (RPS6, RPS14, and RPS3) and large (RPL23a, RPL24, and RPL8) subunits were enriched in the ASFV-DP fraction." (PMID 29021398, 2017). "After 3 h of infection, bacteria were killed with antibiotics and TNF-α was added at 100 ng/ml for 1 h to stimulate RPS3 nuclear translocation." (PMID 20041225, 2009). "Additionally, RPS3, RPS18, and RPL13α are stably expressed in T. castaneum after infection with Beauveria bassiana." (PMID 40266757, 2025). "When the infection was prolonged to 24 h, the interaction between HMGB1 and RPS3 still existed." (PMID 35632744, 2022). "Infection with ΔnleH1 EHEC failed to inhibit RPS3 nuclear translocation, whereas infection with ΔnleH2 was not significantly different from wild type EHEC." (PMID 20041225, 2009). "Importantly, this interaction was specific as rpS3 did not crosslink to another large ribosomal subunit protein rpL36, and was only captured in ribosomes isolated from VSV-infected cells, consistent with increased rpL40 occupancy during infection." (PMID 41279401, 2025).
cancer (37 papers, 2012 to 2025). A tumor composed of atypical neoplastic, often pleomorphic cells that invade other tissues. "RpS3 exists intracellularly in both mouse and human cancer cells and is indigenously secreted after N-linked glycosylation." (PMID 34745438, 2021). "RPS3 exists intracellularly in both mouse and human cancer cells, but it is secreted after its N-linked glycosylation." (PMID 30819254, 2019). "Cis-diamminedichloroplatinum(II) (cisplatin) is a well-known anti-tumor agent, and resistance of some cancer cell lines to this drug is associated with RP uS3 (RPS3), which activates the NF-κB pathway due to an extra-ribosomal function of the protein as a subunit of the NF-κB complex." (PMID 37511213, 2023). "A point mutation at this residue decreased secretion of rpS3 in cancer cell lines." (PMID 27384988, 2016). "The wound healing assay showed the N165G mutation of rpS3 had reduced cancer cell migration." (PMID 27384988, 2016). "The transcriptomic and functional analyses reveal that the downregulation of three genes (HIF1A, COPS5, and RPS3) largely contributes to cancer resistance in MPI." (PMID 38360878, 2024). "Recent reports show that RPS3 mediates the PI3K-Akt signaling axis in cancer cells, which correlates with our findings from the study." (PMID 37396909, 2023). "We identified and validated ribosomal protein S3 (RPS3) as a fucosylated protein in human cancer cells as well as in normal mouse tissues." (PMID 34070332, 2021). "We find that Ribosomal protein S3 (RPS3) is fucosylated in normal tissues and in cancer cells, and that the extent of its fucosylation appears to respond to stress, including MAPK inhibitors, suggesting a new role in posttranslational protein function." (PMID 34070332, 2021). "In several types of cancer, RPS3 as a component of the NF-κB TF contributes to the upregulation of prosurvival genes, radioresistance, and cancer development." (PMID 34831461, 2021). "In this study, we also demonstrated that RPS3 is released from tumor cells following treatment with an anti-cancer drug, and that this released RPS3 can affect the surrounding DCs expressing TLR4 in the tumor microenvironment." (PMID 30819254, 2019). "This study therefore proved that human cancer cell-derived RPS3, a novel TLR4 ligand, has great potential as an adjuvant in tumor-specific antigen DC-based vaccines." (PMID 30819254, 2019). "Based on the findings of this study, we conclude that RPS3 from human cancer cells has a very good effect on the immune system." (PMID 30819254, 2019). "In terms of glycosylation, N glycosylation of Asn165 residue of Rps3, which is secreted in cancer cell lines, regulates the migration and invasive phenotype of the cancer cells." (PMID 28966624, 2017). "Decreased rpS3 protein levels in cells induced changes in the morphology of invasive malignant cancer cells to that of normal cells." (PMID 27384988, 2016). "Although the mechanism of secretion is not well known, the secretion of rpS3 appears to be related to the invasive malignancy of cancer cells." (PMID 27384988, 2016). "RPL19 and RPS3 are both upregulated in high growth situations, specifically in certain cancer cells." (PMID 27830090, 2016). "These genes are involved in the regulation of cell cycle (CCND1, CDCA5, FOSL1, KDM2A, NUMA1, RHOD), apoptosis (FADD, ORAOV1), or the DNA damage response (DDB1, KAT/TIP60, MUS81, PACS1, RPS3), and several have been implicated in the HPV lifecycle and/or HPV-associated cancers." (PMID 40892869, 2025). "Firstly, the overexpression of RPS3 in numerous cancers supports its involvement in tumorigenesis." (PMID 40940922, 2025). "The ribosomal protein S3 (RPS3) is fucosylated in human cancer cells and normal mouse tissue." (PMID 36140189, 2022).
cancer (continued). "Additionally, it has been reported that RPS3 is essential for the induction of chemoresistance in cancer cells." (PMID 35951361, 2022). "Through effective epitope generation of these antibodies and the application of in vitro methods, antibodies against rpS3 could serve as biomarkers in cancer diagnosis and treatment." (PMID 34745438, 2021). "RPS3 has been reported to have a role in progression in several cancer types." (PMID 34070332, 2021). "Ribosomal protein S3 (rpS3), a member of 40S small ribosomal subunit, is a multifunctional protein with various extra-ribosomal functions including DNA repair endonuclease activity and is secreted from cancer cells." (PMID 34745438, 2021). "An initial experiment revealed that RPS3 is expressed in various cancer cells." (PMID 30819254, 2019). "In this study, we identified 40S ribosomal protein S3 (RPS3) through a pull-down assay using a variety of human cancer cell-derived proteins that could bind to TLR4." (PMID 30819254, 2019). "Because secreted rpS3 requires N-glycosylation, we sought to confirm whether glycosylation of rpS3 is related to cancer malignancy." (PMID 27384988, 2016). "Another study has been reported that RPS3 is secreted as a homodimer in cancer cells." (PMID 26336993, 2015). "All these date indicate that RPS3 plays an important role in cancer progress." (PMID 26336993, 2015). "All the reported data suggested that RPS3 may be a putative marker for malignant tumors." (PMID 33644057, 2021). "Thus, RPS3 is a novel and potential adjuvant for DC-based cancer vaccines." (PMID 30819254, 2019). "If these studies are confirmatory, we will know exactly whether rpS3 is secreted by the reduction of interaction with nm23-H1 in aggressive cancer cells and it will be confirmed that the rpS3 protein intracellularly functions as an inhibitor for metastasis related with nm23-H1 pathway." (PMID 27384988, 2016). "This suggests that secreted rpS3 may be a putative marker for malignant tumors." (PMID 27384988, 2016). "Here, the authors examine cancer resistance mechanisms across seven bat species using in vitro and in vivo models, and identify HIF1A, COPS5, and RPS3 as related genes." (PMID 38360878, 2024). "Therefore, antibodies with high specificity against rpS3 protein could be useful cancer biomarkers." (PMID 34745438, 2021). "Ribosomal proteins RPS3 and RPL4, together with FBL (fibrillarin), contribute to ribosome biogenesis, rRNA processing, and translation, linking this module to the increased protein synthesis demands of rapidly proliferating cancer cells." (PMID 41514860, 2025). "Therefore, there is a possibility of adverse effects when RPS3, EIF2S1 and/or RBM8A are targeted in cancer therapy." (PMID 34202873, 2021). "This group showed that the secretion of dimeric RPS3 into the extracellular space and the secretion levels of RPS3 were obviously higher in malignant cancer cells than in normal cells." (PMID 33299138, 2020). "Our functional assay showed that growth suppression was induced in non-cancerous cells by the downregulation of three RBPs (RPS3, EIF2S1, RBM8A), suggesting that these molecules have pivotal functions in proliferation and apoptosis in non-cancerous cells as well as cancer cells." (PMID 34202873, 2021).
tumor (34 papers, 2014 to 2025). "It is concluded that RPS3 is released from tumor cells when treated with an anticancer drug and that RPS3 can associate with TLR4." (PMID 30819254, 2019). "Moreover, RPS3 has been reported to be associated with the radioresistance, chemoresistance and invasive metastasis of tumor cells, but its role in the development of ACC remains poorly understood." (PMID 35847905, 2022). "RPS3 is been reported to be associated with the biological functions of tumor cells." (PMID 35847905, 2022). "Secondly, RPS3 is secreted and glycosylated, and it is the level of glycosylated RPS3 that regulates tumour cell invasion and migration." (PMID 40940922, 2025). "In the colony formation experiment, we also observed that specific knockdown of RAD50/RPS3 protein restored the inhibitory effect of Olaparib on tumor cell proliferation." (PMID 37759323, 2023). "Herein we found that SIAH1 was decreased in EOC tumour tissues and cell lines and negatively correlated with the RPS3 levels." (PMID 35951361, 2022). "The tumor weight of the sh-RPS3 group was significantly lower than that of the control group, and the difference was statistically significant (P<0.05)." (PMID 35847905, 2022). "Animal tumour formation experiments, verified the effects of SIAH1 and RPS3 on tumour growth and development in vivo." (PMID 35951361, 2022). "SIAH1 overexpression resulted in a smaller tumours volume, fewer tumours, lower RPS3 protein expression, higher apoptosis rates and lower proliferation rates." (PMID 35951361, 2022). "This in turn promoted the dissociation of RPS3 from the complex, thereby reducing NF-κB nuclear translocation and inhibiting tumor progression." (PMID 34412652, 2021). "In fact, DAMP proteins binding to TLR4 (e.g., HMGB1, S100, HSPs, API5, and RPS3) have been used as adjuvants for DC-based vaccines, affecting tumor prevention, treatment, and survival." (PMID 33299138, 2020). "For instance, RBP RPS3 was markedly up regulated in HCC tumor tissues and served as a critical tumor-promoting factor via up-regulating SIRT1." (PMID 33575212, 2020). "EG.7 or TC-1 cells were injected subcutaneously into mice, and after establishment of a tumor mass on day 5, RPS3-treated DCs pulsed with OVA or E7 were used to vaccinate the mice using a footpad inoculation once a week for two weeks." (PMID 30819254, 2019). "The RPS3-activated DCs were pulsed with the tumor specific antigens OVA or E7 and were then injected into the footpads of mice." (PMID 30819254, 2019). "More importantly, the tumor treatment effects in mice vaccinated with the RPS3-treated DCs pulsed with OVA or E7 were greater than in mice vaccinated with LPS-treated DCs pulsed with OVA or E7." (PMID 30819254, 2019). "All the mice vaccinated with RPS3-activated DCs pulsed with the OVA or E7 peptides remained tumor-free for 60 days." (PMID 30819254, 2019). "Mouse BMDCs (2 × 10^6) were treated with RPS3 or LPS after which the DCs were pulsed with a tumor specific peptide and then injected into the footpad of mice once a week for two weeks." (PMID 30819254, 2019). "A suppression of tumor growth and the long-term survival was seen in mice injected with RPS3-treated DCs pulsed with OVA or E7 compared to mice injected with untreated DCs or RPS3-treated DCs not pulsed with peptide." (PMID 30819254, 2019). "RPS3 was released from tumor cells following treatment with an anticancer drug, and it was shown that the released RPS3 binds to TLR4." (PMID 30819254, 2019). "After the tumor mass was established, the mice were vaccinated with either RPS3 treated wild type or TLR4−/− DCs pulsed with E7 peptide once a week for two weeks." (PMID 30819254, 2019). "Our previous data demonstrated the secretion of rpS3 into the extracellular space in conjunction with tumor malignancy." (PMID 27384988, 2016).
tumor (continued). "Knockdown of RPS3 significantly suppressed tumor growth and RPS3 protein expression compared to the treatment with the non-specific scramble siRNA." (PMID 26336993, 2015). "Additional studies suggest that RPS3 can act as a tumour suppressor by other mechanisms." (PMID 40940922, 2025). "Tumour cells also exhibit higher levels of glycosylated RPS3 than normal cells." (PMID 40940922, 2025). "Finally, we identified 4 putative tumor-derived Igλ-associated proteins including ribosomal protein L7 (RPL7), ribosomal protein S3 (RPS3), histone cluster 1, H1b (H1-5), histone cluster 1, H1t (H1-6)." (PMID 37784026, 2023). "Among them, the enhanced binding of MRE11:p.K464R mutation to RAD50/RPS3 facilitated non-homologous end joining (NHEJ) repair in tumor cells, thereby expanding the scope of research into acquired resistance to PARP inhibitors." (PMID 37759323, 2023). "Moreover, ectopic expression of RPS3 or depletion of RPS3 ubiquitination mediated by SIAH1 via the K214R mutant significantly impaired cisplatin-induced tumour suppression in cells stably expressing SIAH1." (PMID 35951361, 2022). "As a ribosomal component, RPS3 plays a pivotal role in certain human tumours." (PMID 35951361, 2022). "However, the results of the tumor growth curve showed that the tumor volume of the sh-RPS3 group grew significantly slower than that of the control group, and the tumor was removed out at the end of the experiment on the 35th day." (PMID 35847905, 2022). "Our results indicate that RPS3 may act as a tumour resistance promoter downstream of SIAH1 by promoting NF-κB-induced transcriptional activation, which is considered to contribute to EOC chemotherapy resistance." (PMID 35951361, 2022). "In addition, both upregulation and intrinsic dysfunctions in ribosomes result in an increased incidence of tumors, and RPS3 is involved in radioresistance or invasion of tumor cells." (PMID 33644057, 2021). "Pretreatment of exosomes derived from RPS3-overexpressing SGC7901R cells reduced the inhibitory effect of cisplatin on the tumor growth in compared with cisplatin (0.6 mg/kg) alone, while the pretreatment of exosomes derived from RPS3-silencing SGC7901R cells did the opposite effect." (PMID 33644057, 2021). "In the present study, we screened RPS3 from human tumor cells as a new TLR4 ligand." (PMID 30819254, 2019). "Furthermore, since RPS3 is expressed and released by tumor cells, DC would be activated by tumor lysate which contains RPS3." (PMID 30819254, 2019). "Next, we demonstrated that the number of tumor specific CD8+IFN-γ+ T cells is increased and that both tumor prevention and tumor treatment effects could be achieved using a tumor-specific antigen pulsed DC-based vaccine with RPS3 as an adjuvant." (PMID 30819254, 2019). "However, tumor lysates contain varied DAMPs or inflammatory factors even except RPS3 that can activate DCs." (PMID 30819254, 2019). "Next, we evaluated the effect of the RPS3-treated DC vaccine on tumor treatment." (PMID 30819254, 2019). "Furthermore, we clarified which cytotoxic immune cell make the most significant contribution to the effects of the RPS3-based DC vaccine on tumor prevention using depletion with antibodies against CD4, CD8, and NK." (PMID 30819254, 2019). "Therefore, a vaccine comprised of DCs treated with RPS3 and pulsed with a tumor specific peptide has a significant effect in producing memory T cells." (PMID 30819254, 2019). "Furthermore, DC vaccination with RPS3 and tumor cell specific peptides confirmed the utility of RPS3 as an adjuvant in vivo." (PMID 30819254, 2019). "We also analyzed the effect of RPS3 knockdown on apoptosis in tumor tissues by TUNEL assay." (PMID 26336993, 2015). "Moreover, alizarin red (ARS) staining in tumor tissues showed that knockdown of RPS3 effectively increased the Ca2+ red dots by comparison with the scrimble or control group." (PMID 26336993, 2015).